IL10 (interleukin 10)
Diseases named in the same sentence as IL10 in open-access papers (continued):
Sharing a sentence is not in itself a finding about the gene and the disease.
infection (continued). "Furthermore, while the number of CD4+Foxp3− T cells was similar between the groups on day 8 post infection (data not depicted), CD8+ effector T cells were elevated in the lungs of IL-10−/− mice." (PMID 22393401, 2012). "In contrast to ex-vivo stimulation of human tonsil cells and in contrast to previous studies using GAS-M89, expression of functional SMEZ during intramuscular infection of HLA-DQ8 transgenic mice did not increase local tissue levels of TNFα, IL-10, IL-17 or IFNγ." (PMID 23049698, 2012). "In order to evaluate whether PbAOX suppression could alter the cytokine profile in alveolar macrophages, we determined the gene expression of IL6, IL10, IL12p40, and TNF-α during infection of non-activated and IFN-g-activated alveolar macrophages." (PMID 22039556, 2011). "These include IL10, Cd55 (complement decay-accelerating factor) and Cxcr4 (CXC chemokine receptor 4), which all have plausible roles in the response to infection but there were no published SNP in exons of any of these and no SNP in conserved intergenic regions." (PMID 21085469, 2010). "Single infections with RSV and IAV did not result in a markedly different cytokine production, except that RSV induced higher secretion of the anti-inflammatory cytokine IL-10 than IAV (P < 0.05), and IAV showed a tendency to induce higher levels of the inflammatory cytokine IL-1β than RSV." (PMID 40366152, 2025). "Hence, IL-10+CD8+T effector cells are critical to maintain immune homeostasis, which regulates exaggerated inflammation and tissue damage without affecting viral clearance during later stages of an infection." (PMID 41009359, 2025). "Importantly, the polarization phenotype of U937 macrophages did not change drastically after 8h of infection, although we detected a statistically significant reduction (~30%) in IRF1 expression, concomitant with a ~40% increase in IL-10 in M1 polarized macrophages as compared to M0 controls." (PMID 38808065, 2024). "We used qPCR to analyze 12 host-related genes, including those with no significant fold change (IL12A), modest (e.g. TNF, LMO1, IL10, CCL2, IL1B) or high fold change, including CXCL8 which was among the 50 identified to be most significantly dysregulated in monocytes as a result of infection." (PMID 36747074, 2023). "Moreover, IL-10-nonproducing memory CD4 T cells rapidly upregulated IL-10 expression during recall, with reported potent inhibitory effects on CD4 T cell effector functions during secondary infection." (PMID 33529242, 2021). "Intestinal macrophages isolated from mice in the absence of infection or inflammation do produce low levels of cytokines classically described as proinflammatory, such as TNF and IL6, in response to TLR stimulation but, crucially, they also produce IL-10 to temper their activity." (PMID 33465156, 2021). "Together, these data showed that IL-10 would not impair the production of chemokines that guided CD4+ T cells to the M. tuberculosis–infected lungs but it would inhibit the expression of chemokine receptors essential for CD4+ T cells to enter the lung parenchyma and induce control of infection." (PMID 34554927, 2021). "The infection of adult immunocompetent mice with H. pylori significantly increased the levels of the inflammatory factors IFN-γ, TNF-α, MCP-1 and IL-8, as well as the levels of the regulatory cytokine IL-10 when compared to basal levels in non-infected animals (data not shown)." (PMID 32230910, 2020). "In the absence of pre-existing infections, induction of greater inflammatory response by TFs might favour virus survival within the healthy FGT by driving an influx of target cells to sites of infection while suppressing immune responses via IL-10." (PMID 32615983, 2020).
infection (continued). "Therefore, we quantified the production of cytokines produced by macrophages (IL-6, IL-10, TNFα, IFN-γ, GM-CSF and IL-1β□ in non-infected, Mtb-infection, HIV-infected and co-infected cultures over the course of an Mtb-infection using multiplex cytokine profiling." (PMID 31133636, 2019). "However, there were no increases in IL-4, IL-10, IL-12p70 or IFN-γ, possibly due to the different VZV strains used (VZV Ellen strain in the previous report and the Gilden strain herein) or differential cell type specific responses to infection." (PMID 30786281, 2019). "EV Y inoculation without infection did not stimulate the production of NO, but spleen cells from uninfected mice inoculated with EV Y and stimulated in vitro with TcAg produced lower levels of TNF-α, IFN-γ, IL-10, and IL-6 than did spleens cells from control mice." (PMID 29755471, 2018). "Infection with N. americanus may not affect the levels of IL-4 and arginase-1 (Arg-1) expression by the M2 macrophages, although it results inhigher numbers of CD206+CD23+IL-10+ monocytes." (PMID 30274434, 2018). "As for serum cytokines, cytokine production by macrophages from infected HFD mice at both 1 and 8 weeks post‐infection was significantly less pro‐inflammatory than cytokine production by macrophages from infected ND mice, due to reduced TNF‐α production, but not increased IL‐10 secretion." (PMID 27794208, 2017). "Infection of WT macrophages with N. caninum induced a marked production of IL-6 and TNF-α, and this response was partially suppressed in macrophages lacking Nod2, whereas IL-10 levels were increased in culture supernatants of Nod2−/− BMDMs at the initial replicative cycle of the parasite (8 h)." (PMID 27377650, 2016). "Thus, infection-induced IFN-γ and IL-10 have nonredundant roles in the inhibition of AAI." (PMID 26644379, 2016). "We found that cytokines typically of effector T cell origin (e.g. IFNγ, IL-10, and TNF) were not significantly altered in WT and KO mice, although there was a general trend toward higher cytokine levels in IL-21R KO mice late after infection (i.e. day 14 p.i.)." (PMID 25849970, 2015). "Interestingly, the cytokines whose levels were increased in HMA+ strains during mBMDM infection in vitro and in PECS ex vivo, including IL6, CCL5, and IL10, are not those that would be expected to change based on interference with known mitochondrial signaling pathways (i.e., MAVS, NF-kB, IRF3/7)." (PMID 24781109, 2014). "Furthermore, the lack of the P2X7R during MP287/03 Mbv infection did not affect the low production of IL-1β by lung infiltrating cells, but it restored the CD4+ and CD8+ T cell responses with the secretion of more IFNγ and less IL-10." (PMID 24991816, 2014). "IL-27 limits IFN- γ production by CD4+ T cells during various infections, attenuates the development, but not necessarily maintenance, of Th17 responses by limiting retinoid-related orphan receptor (ROR)c expression and stimulates IL-10 production by multiple effector CD4+ T cell populations." (PMID 23593003, 2013). "At day 4 following CB4 infection of WT NOD mice, we observed significant increases compared to uninfected controls in the levels of both TNF-α and IL-6 and to a lesser extent IFN-γ Little to no production of IL-4, IL-5, IL-10, IL-12p70 was observed following infection (data not shown)." (PMID 19122812, 2009). "Also, the moment of the initial contact with the infection was not considered and cytokine and immune responses may vary at different times on the development of IBD and therefore, the length of the infection might impact IL-10 levels." (PMID 32695157, 2020). "Notably, the inability of NK cell to produce IL-10 did not influence the viral burden in MCMV-infected PKO mice, as PKO-NKp46-Cre-Il10fl/fl had similar virus titer in their spleens and livers as compared with their control littermates PKO-Il10fl/fl at D5 post-infection." (PMID 31803193, 2019).
infection (continued). "As we identified no detectable infection driven expansion of vaccine-specific CD4+ T cell populations during the four day culture, we proceeded to investigate whether we could detect infection specific cytokine response (IFN-γ, IL-1β, IL-6, IL-10, IL-12p70 and TNF-α) in the culture supernatant." (PMID 28588268, 2017). "As we, and others, have shown an important role for IL-10 in limiting immunopathology during malaria infection, we determined whether elevated T-bet expression by effector CD4+ T cells and increased Th1 cell terminal differentiation in WSX-1−/− mice during infection was due to lack of IL-10." (PMID 23593003, 2013). "Interestingly, we found markedly improved T cell responses and clearance of normally chronic LCMV Clone 13 infection when either myeloid cells or T cells lacked IL-10 production and mice depleted of monocytes/macrophages or CD4+ T cells exhibited reduced overall levels of IL-10 mRNA." (PMID 24244162, 2013).
cancer (1,681 papers, 2002 to 2026). A tumor composed of atypical neoplastic, often pleomorphic cells that invade other tissues. "IOIBD mediated by IL-10/IL-10R mutations usually presented as a more malignant disease than VEOIBD, mainly due to an early age of onset, inadequate treatment response, and poor prognosis." (PMID 41425514, 2025). "Chronic inflammation as a hallmark of cancer can be counteracted by IL-10 overexpression modulating excessive inflammation." (PMID 40484866, 2025). "Different cytokines, including TGFβ, IL6, and IL10, as well as cancer-associated metabolites, including tryptophan metabolites, lactate, and prostaglandin E2, inhibit cytotoxic cell functions at various levels." (PMID 40163355, 2025). "We next pursued the design of an IL-10→IL-2 cytokine adaptor since IL-10 is also dysregulated in several cancers and is associated with worse outcomes in cancer patients." (PMID 40069219, 2025). "The positive association between cancer and IL-10 was mediated 5.6% by TNFR1 and 4.1% by IL-6 independently, while the positive association for GDF15 was mediated 36.1% by TNFR1 and 10.5% by IL-6 independently." (PMID 41280118, 2025). "The underlying mechanisms lie in that cancer cells can secrete cytokines, such as IL10, IL12, IL 6, and TNF, facilitating M2-like polarization, then exerting immunosuppressive effects, and finally accelerating cancer progression." (PMID 39963673, 2025). "Researchers are developing various targeted strategies and drugs for inflammatory diseases and cancer caused by dysregulation of IL-10 and IL-10R pathways." (PMID 41300695, 2025). "After the carcinoma is in an advanced stage and has already caused a more severe lesion, there is less secretion of IL-10." (PMID 41379186, 2025). "Some of these IL-10 variants have been associated with either low or high expression in several cancer types." (PMID 38186186, 2024). "In all three of these cancers, the association appears to be at least partly mediated through IL-10." (PMID 38527997, 2024). "In this study, we investigated the associations between the expression levels of PD-L1 and IL-10 in the peripheral blood mononuclear cells (PBMCs) and cancer tissues of GC patients." (PMID 38197259, 2024). "Prior to the onset of EC, IL-10 likely acts as a protective factor by reducing chronic inflammation and, consequently, lowering the risk of cancer development." (PMID 39496002, 2024). "Tregs show interaction with MDSCs in cancer, and the activation of Tregs by MDSCs is mainly caused by cytokines, such as IL-10 and TGF-β, which are also associated with the induction of MDSCs53." (PMID 38213716, 2024). "Mounting evidence indicates that C. sinensis infection drives Th2 immune responses and facilitates the production of the cytokines IL-13, TGF-β, IL-10 and IL-4, which have been implicated in promoting cancer stemness." (PMID 38285640, 2024). "Components such as collagen, laminin, and fibronectin are integral to the TME structure, alongside extracellular matrix elements, cancer-associated fibroblasts (CAFs), and immunosuppressive cytokines like IL-10 and IL-17." (PMID 38909166, 2024). "IL-10 has been correlated with increased suppression of T cells in cancer patients and associated with worse survival." (PMID 39502689, 2024). "It has been observed that the expression of IL-10 is either overexpressed or deficient under various pathophysiological conditions, depending on the specific cancers being analyzed." (PMID 38339076, 2024). "Inflammation is closely linked to the cancer progression, with neutrophils considered a source of IL-10." (PMID 38279997, 2024). "Studies have linked IL-10 polymorphisms to various cancers, including head and neck, laryngeal, gastric, and hematological neoplasms." (PMID 39118076, 2024). "Early-stage infiltration of M1 macrophages is often associated with increased IL-12 and decreased IL-10 levels, which enhances immune responses and cancer cell destruction." (PMID 39575419, 2024).
cancer (continued). "Inflammatory mediators, including tumor necrosis factor-alpha (TNF-α), interleukin-6 (IL-6), and interleukin-10 (IL-10), have been implicated in cancer metastasis." (PMID 38116560, 2023). "IL-10, an immunosuppressive cytokine secreted by Tregs and some cancer cells, is associated with poor prognosis in many cancers." (PMID 37649480, 2023). "High levels IL-4, IL-10, and IL-6 expression have been linked to the development of several cancer types, improved EMT, and the development of treatment resistance via the triggering of anti-apoptotic pathways and metastasis." (PMID 37941832, 2023). "Future research should evaluate potential differences in these associations across sex and age and determine the impact of cancer on functional changes in IL-10 action." (PMID 37568698, 2023). "Several inflammatory mediators, such as tumor necrosis factor-alpha, interleukin (IL)-6, and IL-10, have been linked to cancer initiation and progression." (PMID 36836114, 2023). "Cytokines such as tumor necrosis factor-alpha (TNF-α), interleukin-6 (IL-6), and IL-10 have been linked to cancer spread." (PMID 36771154, 2023). "IL-10 also suppresses cancer-associated inflammation, making it a key player in the host’s fight against cancer." (PMID 38011277, 2023). "High levels of C-reactive protein (CRP), interleukin 6 (IL- 6), and interleukin 10 (IL-10) are associated with poor performance, weight loss, and worse prognosis in cancer patients." (PMID 38067294, 2023). "Low levels of anti-inflammatory cytokines, such as IL-10 and IL-4, have also been linked to chronic pain in patients but have been studied less in the context of cancer-related pain." (PMID 37887537, 2023). "In recent years, the relationship between IL-10 and IL-6 gene polymorphisms and cancer have attracted great attention." (PMID 37077342, 2023). "In the present study, the IL-10 rs1800896 polymorphism showed different impressions in diverse organs, probably because of the IL-10 rs1800896 gene polymorphisms in different parts of the body having different distributions in different cancer types." (PMID 37077342, 2023). "Investigations have shown that the IL-10 promoter region polymorphisms affect IL-10’s gene transcription and translation, resulting in abnormal cell proliferation and cancer development." (PMID 36009467, 2022). "The results showed that both CCL13 and IL10 expression are significantly associated with the infiltrating immunosuppressive cells in all four cancers, including KIRC." (PMID 35692780, 2022). "The IL-10 promoter region polymorphisms affected IL-10 gene transcription and translation, resulting in abnormal cell proliferation and cancer development." (PMID 35186043, 2022). "Numerous studies have investigated the association between the polymorphisms of IL-10 as potential biomarkers in different types of cancer." (PMID 36009467, 2022). "This specific cytokine pattern appears to have a prognostic effect, as high interleukin 6 or interleukin 10 serum concentrations are associated with poor prognosis in independent cancer types." (PMID 36579330, 2022). "In the resectable cohort, RANTES, TIMP-1, FGF-4, and IL-10 individually differentiated patients according to their cancer-associated survival." (PMID 36497475, 2022). "In the setting of cancer, IL10 causes immunosuppression, which decreases T cell proliferation by inhibiting antigen-presenting cells." (PMID 35741689, 2022). "The cytokine ratio, IL-10/IL-6 has been previously reported as a marker of immunosuppression associated with malignant tumors and/or with intense physical exercise." (PMID 35327367, 2022). "This is due to the fact that macrophages produce IL6 and IL10, which, respectively, cause cancer cell proliferation and inhibition of cytotoxic T cells." (PMID 35629230, 2022). "As a double-edged sword, the immunoregulatory cytokine IL-10 is implicated in either cancer promotion or inhibition, depending on the context during carcinogenesis." (PMID 36437782, 2022).